EPCAM (epithelial cell adhesion molecule)
Diseases named in the same sentence as EPCAM in open-access papers (continued):
Sharing a sentence is not in itself a finding about the gene and the disease.
breast carcinoma (continued). "Nonetheless, in contrast to ovarian cancer and colorectal cancer, EpCAM was absent in the exosome isolated from the breast cancer patients’ serum." (PMID 32046162, 2020). "The specificity of the antibodies for epithelial (EpCAM, E-cadherin, CK8, CK18, and CK19) and mesenchymal (vimentin, fibronectin, and N-cadherin) markers used in the negFACS-IF:E/M platform were initially validated in various breast cancer cell lines." (PMID 32296584, 2020). "In contrast, in at least one study of prostate and breast cancer patients, only the EPCAM-high and not the EPCAM-low cells were related to survival, while others have found that the prognostic value of mesenchymal CTCs is subtype specific." (PMID 33095819, 2020). "Moreover, in primary human luminal breast cancer, the metastasis-initiating cells containing CTC that express EPCAM, CD44, CD47, and the proto-oncogene MET are related with reduced overall survival (OS)." (PMID 31261917, 2019). "MMPs, ADAMs, HES1/2, HEY1, c-Myc, CD44, EpCAM and Vimentin (downregulation of E-cadherin) engage in survival, stemness, EMT, invasion, ECM degradation/remodeling, angiogenesis, intravasation/extravasation, and metastatic colonization in breast cancer." (PMID 31694640, 2019). "CTC negative for EpCAM, but expressing different stem-like markers, were found directly involved in increased brain metastatic properties using breast cancer and lung cancer PDX models." (PMID 31636732, 2019). "To test whether this is a broader effect in basal-like breast cancer cells, we sorted another cell line, SUM149, into EpCAM+ basal-like cells and EpCAM− claudin-low cells." (PMID 31822725, 2019). "In breast cancer, CTCs have been defined in a variety of ways, most commonly based on the presence of EpCAM or epithelial cytokeratins, and the absence of CD45." (PMID 35582279, 2019). "EpCAM expression is decreased upon EMT activation and in some aggressive breast cancer cell lines, including normal-like cell lines (e.g., MDA-MB-231, SK-BR-7, BT549), which suggests that EpCAM-based CTCs detection may be insufficient." (PMID 30634453, 2019). "We quantified the EPCAM and keratins CTC markers, in a PDX cohort of breast cancer." (PMID 30450210, 2018). "Breast cancer stem cell (BCSC)-specific markers were highly reduced upon VDAC1 silencing in tumours established from the TNBC MDA-MB-231cell line, including ALDH1, CD133, EPCAM, SOX2 and KLF4." (PMID 30544833, 2018). "The patterns of mHsp70 and EpCAM expression by MDA-MB-231 (mHsp70: 50 ± 3%, EpCAM: 90 ± 2%), MCF7 (mHsp70: 51 ± 6%, EpCAM: 99 ± 4%), and T47D (mHsp70: 25 ± 7%, EpCAM: 98 ± 5%) breast cancer cells that were analyzed at TUM and NTU were nearly identical (data not shown)." (PMID 30443493, 2018). "The EpCAM+, CD24−, CD44+, and ALDH+ populations across different subtypes of breast cancers represent anatomically distinct BCSCs with respective EMT (epithelial-to-mesenchymal transition) and MET (mesenchymal-to-epithelial transition) gene expression profiles." (PMID 29258583, 2017). "EpCAM is an epithelial cell-specific marker which is highly expressed in breast cancer, prostate cancer and colon cancer but not in RCC." (PMID 27494883, 2016). "Recently, the clinical relevance of CTCs in metastatic cancers has been clearly demonstrated in multiple types of advanced cancer including breast cancer, prostate cancer and colon cancer, where CTC detection has been significantly enhanced by the development of EpCAM-based enrichment strategies." (PMID 27494883, 2016). "For instance, we have previously reported that EpCAM-negative breast cancer cells express high amounts of EMT-related genes." (PMID 27013581, 2016). "In a mouse model of human breast cancer using EpCAM positive and negative cell lines, the number of CTCs captured correlated positively with the size of the primary tumor and was independent of their EpCAM expression." (PMID 27501846, 2016).
breast carcinoma (continued). "Using our p-MOFF system, we demonstrated efficient isolation of CTCs regardless of heterogeneous EpCAM expression in breast cancer patient blood samples." (PMID 27013581, 2016). "Moreover, the presence of EpCAM-/CD49f + cells has recently been shown to increase metastatic potential and to reduce disease-free survival of breast cancer patients; MDA-MB-231 cells are classified as EpCAM−/CD49f +." (PMID 27001172, 2016). "Moreover, CTCs isolated from breast cancer patients using a label-free microfluidic flow fractionation device had differing expression patterns of EpCAM, indicating that affinity approaches reliant on EpCAM expression may underestimate CTC number and potentially miss critical subpopulations." (PMID 27013581, 2016). "Recent quantitative study performed by flow-cytometry demonstrated that bladder T24 and melanoma SK-Mel-28 cancer cells showed low and non-expression of EpCAM, respectively, compared to that on SK-BR-3 breast cancer cells." (PMID 26718583, 2015). "Here, we report the isolation of subsets of EpCAM-negative breast cancer CTCs containing stem-cell properties (CD44+/CD24−) by multiparametric flow cytometry with a combinatorial uPAR and int β1 expression and their abilities to grow long-term in vitro." (PMID 26631983, 2015). "The anti-tumor efficacy of EpCAM aptamer-siEpCAM chimera (EpApt-siEp) was evaluated by qPCR, northern and Western blotting in WERI-Rb1- RB cell line, primary RB tumor cells and in MCF7- breast cancer cell line." (PMID 26176230, 2015). "Similarly the expression of EpCAM in MCF-7 has also been studied earlier, and the binding of EpCAM aptamer to breast cancer cells, MCF-7 cell line is published." (PMID 25576037, 2015). "For example, multiparametric flow-based sorting, including labeling of multiple cell surface markers on breast cancer CTCs, led to the identification of a possible signature of brain metastasis among EpCAM-negative cells." (PMID 25133137, 2014). "Given the interest in the therapeutic potential of EpCAM targeted therapies in cancer management and the limited understanding of the role and expression pattern of Ep-ICD in breast cancer, our study helps to shed light on this widely-studied, yet not fully understood protein." (PMID 25265904, 2014). "CellSearch® is a semiautomated method that isolates CTCs by firstly applying an antibody for the epithelial cell adhesion molecule, EpCAM, which is often present on carcinoma cells including breast cancer, but not present on normal blood components." (PMID 24670368, 2014). "Some breast cancer cell lines are cellularly heterogeneous and contain mixed populations of cells, therefore, we sorted the basal-like SUM149 cell line into two distinct populations based on expression of EpCAM and CD49f." (PMID 23975155, 2014). "Noteworthy, healthy tissue displays mainly weak expression of basic, not glycosylated EpCAM protein, whereas in tumor tissue, as well as in breast cancer cell lines, EpCAM is glycosylated and/or hyperglycosylated." (PMID 23758908, 2013). "By ChIP with chromatin from MDA-MB231 breast cancer cells, we could show that endogenous ZEB1 binds to the native promoter region of EPCAM that has five putative binding sites (E-boxes 1–4 and Z-Box-1) for ZEB1." (PMID 23667256, 2013). "Epithelial cell adhesion molecule (Ep-CAM)-positive exosomes have been collected from the serum from lung and ovarian cancer patients, and HER2-positive exosomes have been isolated from HER2 overexpressing breast cancer cells using this method." (PMID 23839094, 2013). "This dual regulation system for transgene involving EpCAM and let-7 miRNA can be used, not only in retinoblastoma and breast cancer cell lines but any EpCAM positive and let-7 negative cancer cells." (PMID 24391761, 2013).
breast carcinoma (continued). "EpCAM negative breast tumor spheres have been generated from primary tumors, and EpCAM negative, immortalized epithelial breast cancer stem cells have been reported previously (Weinberg R, EMT and Cancer Progression Meeting, Arlington, VA, 2010)." (PMID 23042145, 2012). "Moreover, EpCAMlow breast carcinoma cell lines with mesenchymal phenotype (MDA-MB-231, Hs578t) and inducible overexpression of EpCAM were used to study effects on proliferation, migration and in vivo growth." (PMID 23110550, 2012). "In contrast, in vitro proliferation of EpCAMlow mesenchymal breast cancer cell lines is independent of EpCAM." (PMID 23110550, 2012). "Finally, basal-like and normal-like breast cancer cell lines with a mesenchymal EMT phenotype such as MDA-MB 468 and MDA-MB 231, respectively, also lack EpCAM expression." (PMID 23042145, 2012). "The highly tumorigenic as well as the weakly tumorigenic cell models were EpCAM negative and profiling analysis revealed a normal-like to basal-like breast cancer origin." (PMID 23042145, 2012). "We found that human glioblastoma cells do not express EpCAM contrary to breast cancer cells as expected." (PMID 21987585, 2011). "Mucin 1 (MUC1), a membrane bound glycosylated phosphoprotein predominantly expressed by epithelial cells, is suggested to be a marker for detection of breast-cancer cells not expressing EpCAM." (PMID 21816090, 2011). "Hs578T and MDA-MB-231 cells were found to express none or only very little EpCAM mRNA and protein in comparison to established and well characterized breast cancer cell lines such as MCF-7 or SK-BR-3." (PMID 21281469, 2011). "In CA1a and MCF-7 breast cancer cells, specific ablation of EpCAM decreased phosphorylated c-Jun, but had no significant impact on total c-Jun." (PMID 22132731, 2011). "Of note, most other commercially available human breast cancer cell lines are characterized by a high level of EpCAM protein expression, thus low or even no EpCAM expression is a rare occurring property." (PMID 21281469, 2011). "Our results show the effect of constitutive EpCAM expression in previously EpCAM antigen negative or low expressing parental human breast cancer cell lines Hs578T and MDA-MB-231." (PMID 21281469, 2011). "It has been shown that normal-like breast cancer cells characterized by aggressive behaviour and worse treatment options are not recognized by the CellSearch circulating tumor cell test (Veridex LLC, San Diego, CA), which uses EpCAM for cell isolation." (PMID 21129172, 2010). "Adecatumumab was unique in that it bound to an epitope encoded by exon 5 of EpCAM, and by inhibiting proliferation of MCF-7 breast cancer cells in the absence of effector cells and complement." (PMID 21044305, 2010). "While we indeed observed the presence of all four of these differentiation states within the panel of human breast cancer cell lines, the majority of cell lines failed to retain Luminal 1 EpCAM+/CD49f- cells." (PMID 20964822, 2010). "G Gastl (Innsbruck, Austria) reviewed the expression of EpCAM in human breast cancer and its strong negative correlation with survival parameters in node-positive patients." (PMID 17211480, 2007). "EpCAM expression was detected in the majority of breast cancer specimens, with 26% showing high expression, 29% medium expression, and 31% low expression, indicating that EpCAM-NIR-PIT could be applicable to a large proportion of breast cancer cases." (PMID 40792441, 2025). "There was a 3.4-fold and 3.1-fold increase in HPA binding of EpCAM-positive plasma-enriched sEVs from individuals with metastatic and stage 2 non-metastatic breast cancer, respectively, compared to that seen in samples from healthy individuals (p < 0.0001 and p < 0.001, respectively)." (PMID 40411659, 2025).
breast carcinoma (continued). "Pathologically elevated EpCAM expression orchestrates a coordinated oncogenic program involving HtrA2 downregulation-mediated apoptosis resistance, PD-L1 upregulation, Treg recruitment, and CD8+ T cell functional impairment, collectively facilitating immune evasion in breast carcinoma." (PMID 40508038, 2025). "In vitro studies revealed that cell migration and invasion are inhibited in breast cancer cells null for the oncogene lysine‐specific demethylase 2A (KDM2A), via TET2‐mediated activation of the downstream tumor suppressors E‐cadherin and epithelial cell adhesion molecule (EpCAM)." (PMID 40116537, 2025). "In 100 early breast cancer patients, the prognostic significance of the level of one of the main EMT transcription factors, TWIST1, was also investigated together with some stem cell transcripts, such as CD24, CD44, and ALDH1, in enriched EpCAM+ CTCs, obtaining promising results." (PMID 39335650, 2024). "In addition, anti-EpCAM CAR-T cells demonstrated significant anti-tumor activity against CSCs of EpCAM solid tumors (e.g., colon cancer, breast cancer, etc.)without significant systemic toxicities." (PMID 39776907, 2024). "Additionally, EpCAM was shown to be overexpressed on breast cancer cells in comparison to non-cancerous breast cells." (PMID 38425422, 2024). "At the same time, the combination of Claudin and EpCAM increases, promotes the phosphorylation of PI3K/Akt and p38, promotes the activation of MAPK and PI3K/Akt pathways, promotes the process of EMT, reduces Apoptotic ability of breast cancer cells, promoting cell proliferation." (PMID 37904877, 2023). "Epithelial and breast cancer-related genes failed to predict response to therapy and disease progression when assessed in EpCAM-based enriched CTCs in patients with metastatic breast cancer starting first-line cisplatin-based therapy or treated with anthracycline and taxane." (PMID 36428760, 2022). "Thus, the post-hypoxia/oxidative stress [SPm (hox)+/ABCG2+ CSCs of several cell lines that we previously characterized for the TS phenotype SPm (hox) enriched in EpCAM+/ABCG2+ CSCs], including oral cancer, breast cancer, and lung cancer, were infected with Mtb-m18b and BCG." (PMID 36248858, 2022). "Furthermore, demonstrating that the TT-RBC-NPs had excellent targeting ability to EpCAM overexpressed breast cancer cells over non-targeted cells, which resulted in higher penetration and cellular uptake." (PMID 36235009, 2022). "Furthermore, Exo also contain some specific proteins that mirror the cell type from which they originate, such as epithelial cell adhesion molecule (EpCAM), melanoma antigen recognized by T cells 1 (Mart-1), human epidermal receptor (HER) (breast cancer, and pancreatic cancer origin)." (PMID 34943819, 2021). "Thus, the first CTCs primary culture was established in 2013 from advanced breast cancer patients using CTCs negative for the epithelial marker EpCAM." (PMID 34071445, 2021). "Several EpCAM-targeting DARPins conjugated to PE40 (ETA”) were developed and showed strong anti-tumor responses in vivo: Ec4-ETA” in HT-29 colon cancer cells and in SW2 small cell lung carcinoma xenografts, Ec1-ETA” and its PEGylated version PEG20kDa-Ec1-ETA” in MDA-MB-468 breast cancer xenografts." (PMID 34439094, 2021). "Microarray analysis of breast cancer cells with ZMYND8 knockout by siRNA revealed that depletion of ZMYND8 reduces the expression of terminal differentiation markers, such as epithelial cell adhesion molecule (EPCAM) and cytokeratin 18 (CK18), by 80% and 86%, respectively." (PMID 33670804, 2021). "Therefore, we sought to differentiate between EpCAM+ cells of breast cancer patients and noncancer patients." (PMID 33020483, 2020).
breast carcinoma (continued). "In our previous studies, sensitive imaging of breast cancer cells of MCF-7 and MDA-MB-231 was obtained using a hole-arrayed plasmonic chip under an epifluorescence microscope, in which one kind of membrane protein, an epithelial cell adhesion molecule (EpCAM), was observed with APC-labeled antibody." (PMID 32580380, 2020). "Importantly, EpCAMlow, CK+ CTCs identified after size-based separation of EpCAM-depleted blood samples did not correlate with clinical outcomes in metastatic non-small cell lung, prostate, and breast cancer." (PMID 32787900, 2020). "The emergence of breast cancer CTCs that do not fit within the widely accepted EpCAM-positive or epithelial cytokeratin-positive definitions demonstrates the importance of considering broader definitions of CTCs for better prognostic and predictive application of CTC enumeration." (PMID 35582279, 2019). "TNBC accounts for up to 20% of breast cancer cases and despite its heterogeneity, three receptors are commonly overexpressed, namely the EGFR1 (in up to 70% of TNBC cases), the epithelial cell adhesion molecule (EpCAM) and chondroitin sulfate proteoglycan 4 (CSPG4)." (PMID 31756933, 2019). "On a logarithmic scale the response of ADSCs was almost linear whereas especially healthy mammary epithelial cells and BCC, EpCAM-positive breast cancer cells, but also MES seemed to have a more sigmoidal nonlinear regression fit (plotted using GraphPad 7.00; nonlinear fit, variable slope)." (PMID 30567518, 2018). "Virtually all of the EpCAM+ and/or CD90+ selected cells coexpressed CD44, a marker associated with epithelial-to-mesenchymal transition and tumorigenic breast cancer stem cells, and CD146 (not shown, 83.5±9.8%), a marker associated with epithelial-to-mesenchymal transition in breast cancer." (PMID 28721373, 2016). "Here we show EMT-induced breast cancer cells maintained in prolonged mammosphere culture conditions possess increased EMT markers and cancer stem cell markers, as well as reduced cell mass and size by quantitative phase microscopy; however, EpCAM expression is dramatically decreased in these cells." (PMID 27013581, 2016). "By labeling CTCs with other specific surface antibodies, such as the human epidermal growth factor receptor 2 (HER-2) in the case of breast cancer (see section “Isolation of CTCs from patients”), or even with an antibody cocktail, the probability to capture EpCAM negative cells will increase." (PMID 26493176, 2015). "Its usefulness in breast cancer has been firmly established, although its dependence on positive selection of EpCAM-positive CTCs may lead to false-negative or false-low CTC results in some patients." (PMID 25358515, 2014). "However, the role of EpCAM in the chemosensitivity of breast cancer MCF-7 cells has not been investigated in vitro." (PMID 25019346, 2014). "However, the effect of EpCAM on cell proliferation and apoptosis in breast cancer cells has not been assessed to date." (PMID 25019346, 2014). "However, several markers, including CD133, CD24, CD44, CD166, EpCAM (CD326), CXCR4 (CD184), c-kit (CD117), and among others have been identified as surface markers of CSCs isolated from glioblastoma, breast cancer, pancreatic cancer, prostate cancer, or hepatocellular carcinoma." (PMID 24675390, 2014). "Furthermore, there is evidence that “normal-like” breast cancer cell lines do not express EpCAM, in comparison with other intrinsic subtypes, and hence can be missed using this antibody alone." (PMID 24670368, 2014). "Here we report a newly developed EpCAM RNA aptamer, also known as a chemical antibody, which is not only specific but also more sensitive than current antibodies for the detection of EpCAM in formalin-fixed paraffin-embedded primary breast cancers." (PMID 23460885, 2013). "Therefore, EpCAM expression should not be considered as an in vivo tumorigenicity marker for normal-like to basal-like breast cancer stem cells." (PMID 23042145, 2012).